PTH (parathyroid hormone)
Diseases named in the same sentence as PTH in open-access papers (continued):
Sharing a sentence is not in itself a finding about the gene and the disease.
Hypoalbuminemia (23 papers, 2002 to 2026). The concentration of albumin in the blood circulation is below the lower limit of normal. "Finally, subgroup analysis further confirmed that patients with aged 65 and over or hypoalbuminemia remained two major risk factors for the development of first episode of peritonitis under different settings of serum PTH/Ca or PTH/P combinations." (PMID 33441921, 2021). "Since P1NP representative of osteoblast activity, and it was deduced that higher osteoblastic activities related with hypoalbuminemia among these PTH groups." (PMID 31839746, 2019). "The present study demonstrated that significant hypoalbuminemia and inflammation occurred among PTH>600 pg/mL group compared to other PTH groups." (PMID 31839746, 2019). "We determined the influence of hypoalbuminemia (albumin≤3.5 g/dL) and normoalbuminemia (albumin>3.5 g/dL) on the bone formation and resorption markers in different PTH groups." (PMID 31839746, 2019). "In conclusion, hypoalbuminemia represents a chronic inflammation which differently relates to bone turnover markers according to serum PTH levels in SHPT patients." (PMID 31839746, 2019). "Serum FGF23 levels were significantly increased in hypoalbuminemia PTH 150-300 and 300-600 groups than normoalbuminemia patients." (PMID 31839746, 2019). "Hypoalbuminemia can directly and indirectly influence the bone metabolism and diminish transfer of minerals in bone tissue, resulting in reduced formation of hydroxyapatite crystals, which also affects the metabolism of PTH and vitamin D." (PMID 31933638, 2019). "Increased age and hypoalbuminemia (serum albumin < 3.7 g/dL versus ≧ 3.7 g/dL) were two significant risk factors for the development of first episode of peritonitis in the multivariable model, but low serum PTH alone was not a risk factor." (PMID 33441921, 2021). "Hypoalbuminemia, as a marker of chronic inflammation, differentially influences the bone markers OPG and P1NP in hemodialysis patients among different PTH groups." (PMID 31839746, 2019). "No protein-energy malnutrition or hypoalbuminemia occurred; however, a late rise in parathyroid hormone and a return of 25-OH vitamin D toward preoperative insufficient values by 60 months indicate the need for sustained micronutrient surveillance." (PMID 42278889, 2026). "With severely high PTH levels (PTH>600), the influence of hypoalbuminemia on P1NP was no longer detected and overwhelmed by influence of PTH and uremic toxins on bone cells." (PMID 31839746, 2019). "Hypoalbuminemia significantly increased the fibroblast growth factor-23 (FGF-23) and procollagen type 1N-terminal propeptide (P1NP) in PTH ≤150 pg/mL, PTH 150-300 pg/mL, PTH 300-600 pg/mL groups, whereas no such relation was noted among PTH> 600 ng/dL group." (PMID 31839746, 2019).
renal dysfunction (23 papers, 2018 to 2026). "As a result of renal dysfunction, serum levels of phosphorus increase, whilst calcium and calcitriol decrease, stimulating the parathyroid glands to secrete high levels of parathyroid hormone (PTH)." (PMID 41521976, 2026). "To minimize confounding effects on calcium and vitamin D metabolism, we excluded patients with renal dysfunction and abnormal PTH." (PMID 40421141, 2025). "The present study included patients with eGFRs ≥60 mL/min/1.73 m2 to eliminate the impact of renal dysfunction on PTH levels." (PMID 32118376, 2020). "For example, there is a large accumulation of parathyroid hormone (PTH) in the blood when patients have renal dysfunction." (PMID 30429775, 2018). "Elevated levels of parathyroid hormone, cytokines, and uremic toxins in the context of renal dysfunction may suppress CYP activity, Phase II metabolic reactions, and drug transport processes." (PMID 40904368, 2025). "We demonstrated a correlation between aging and an increase in PTH values in a population with vitamin D sufficiency, normal serum calcium, and without renal dysfunction." (PMID 37286864, 2023). "We observed a correlation between aging and PTH increase, when measured by a second-generation immunoassay, regardless of vitamin D levels, if greater than 20 ng/mL, in normocalcemic individuals without renal dysfunction." (PMID 37286864, 2023). "Unlike renal dysfunction, an independent relationship between sUA and PTH was quite unexpected." (PMID 34362049, 2021). "Decreased renal clearance due to renal dysfunction, in addition to higher synthesis in the liver, thymus, spleen, and bone due to non-classic regulators of FGF23 production (PTH, vitamin D, and phosphate), would explain the acute increase in plasma FGF23 in AKI." (PMID 37892163, 2023).
Cognitive impairment (22 papers, 2013 to 2026). Abnormal cognition is characterized by deficits in thinking, reasoning, or remembering. "Differently from idiopathic HypoPT, in which a severe cognitive impairment has been shown, in PS-HypoPT, the cognitive involvement is more nuanced, probably because of the longer and more pronounced PTH deprivation in the idiopathic variant." (PMID 38392648, 2024). "Among individuals with normal renal function, elevated PTH is associated with cognitive impairment and improves with treatment." (PMID 38707996, 2023). "Although not supported by all studies, there is evidence from surgical studies that parathyroidectomy, which if successful leads to normalization of PTH and calcium levels, is associated with significant improvement in cognitive function or even reversibility of cognitive deficits." (PMID 26010883, 2015). "This has led some investigators to examine cognitive decline and dementia among ESKD patients who have a high incidence of cognitive impairment and significantly higher PTH levels compared to those with normal renal function." (PMID 38707996, 2023). "While the exact mechanism of cognitive decline in patients with SHPT is likely multifactorial, several studies attempted to identify the role of PTH in cognitive impairment." (PMID 38707996, 2023). "The details of these relationships between cognitive impairment and serum biomarkers, such as PTH and serum calcium, merit further investigation." (PMID 37923800, 2023). "And in addition to the familiar effects of PTH on bone, there are many studies that have found a correlation between PTH and cognitive impairment." (PMID 37993797, 2023). "Excessive parathyroid hormone is considered neurotoxic and results in cognitive impairment; high parathyroid hormone increases calcium influx in the brain, affecting the neurotransmission of the central nervous system and leading to neurotoxicity." (PMID 33132823, 2020). "Of note, all patients with deletions displayed brachydactyly and cognitive impairment, and 3 of these patients also displayed mild resistance to PTH, extremely elevated phosphate levels and exhibited 25-OH vitamin D levels within the normal range." (PMID 31555217, 2019). "This case represents the extreme end of the spectrum of cognitive impairment in PTH dysfunction and defines a possible novel form of PHP1b resulting from the impaired interaction between PTH and PTH1R." (PMID 27415614, 2016). "In summary, the index case reported here represents the extreme end of the spectrum of cognitive impairment in PTH dysfunction and is a dramatic example of refractivity to treatment." (PMID 27415614, 2016). "Serum and CSF levels of calcium, PTH, and 25-hydroxyvitamin D (25OHD) in the study population of 52 patients with cognitive impairment (AD, n=28; other dementias, n=12; SMCI, n=12) and 17 healthy matched controls." (PMID 24312390, 2013). "While some observational studies suggest a link between elevated serum parathyroid hormone (PTH) levels and an increased risk of cognitive impairment or dementia, in this study, we did not observe differences in PTH levels between the CI and NCI groups." (PMID 39717345, 2024). "Therefore, the PTH threshold at which SHPT may lead to cognitive impairment remains unclear." (PMID 38707996, 2023). "More information has been obtained on hormonal resistance classically involved in PHP (PTH, TSH, GHRH and GnRH) and on cognitive impairment, while a few data has been collected on bone mineral status, calcitonin levels and glucolipid metabolism." (PMID 33663571, 2021).
hypothyroidism (22 papers, 2014 to 2026). Abnormally low levels of thyroid hormone. "Based on the available literature and our previous findings, GBHs induced hypothyroidism, bone disturbances and deficiency of hormones responsible for phospocalcic metabolism, such as vitamin D (Vit D) and parathyroid hormone (PTH)." (PMID 41012373, 2025). "Euthyroid sick syndrome, hypothyroidism, hypocalcemia, impaired parathyroid hormone secretion, and vitamin D deficiency appear to be common among the adult HIV-infected patients." (PMID 24587936, 2014). "In fact, it is known that hypothyroidism can cause resistance to PTH." (PMID 38126603, 2023). "Laboratory tests indicated low vitamin D levels, slightly elevated parathyroid hormone, and hypothyroidism." (PMID 38172929, 2024). "The patient had hypothyroidism and hyperprolactinemia, but his blood glucose and parathyroid hormone levels were within normal ranges." (PMID 39109224, 2024). "Additionally, the increased inflammation can disturb the endocrine regulatory axis, leading to hypothyroidism and insufficient parathyroid hormone secretion." (PMID 39071711, 2024). "It is known that excess of THs stimulates bone resorption, increasing the blood values of calcium and phosphorus and suppressing PTH secretion whereas in hypothyroidism the bone turnover is decreased, the serum calcium concentration tends to be lower, and PTH secretion activated." (PMID 34603080, 2021). "In our case, PTH, TSH, and probably GHRH resistance were found at the same time, which induced electrolytes disturbance, hypothyroidism." (PMID 35600030, 2022). "Patients with AIDS have increased prevalence of nonthyroidal illness, hypothyroidism, and abnormal serum parathyroid hormone (PTH) and serum calcium levels." (PMID 24587936, 2014). "There were also variations within each subgroup that may impact the burden of illness, such as other comorbidities, duration of time with HP, and a high proportion of participants without hypothyroidism who were taking PTH replacement therapy (8/11, 73%)." (PMID 32833143, 2021). "Therefore, hypothyroidism would imply a lesser development of the disease since having less circulating PTH would not be able to stimulate the uptake of fructose in the renal cortex, which could have healing implications." (PMID 38534968, 2024).
liver disease (22 papers, 2012 to 2025). "Liver disease was associated with an increased rate of PTH retesting, and dementia with a decreased rate of 25D retesting." (PMID 33912763, 2021). "In some individuals with advanced liver disease, impaired liver function can lead to decreased hydroxylation of vitamin D3 to its active form (D25), resulting in elevated levels of parathyroid hormone." (PMID 37829687, 2023). "Major exclusion criteria were pediatric samples (<18 years) and factors affecting 25-(OH)D and/or PTH levels (i.e., kidney injury, liver disease, PTH disorders)." (PMID 37359435, 2022). "Patients with liver disease had significantly increased HRs for testing for PTH and P (and a point estimate >1 for testing for 25D)." (PMID 33912763, 2021). "Liver disease can also contribute to bone disorders through impaired vitamin D synthesis which results in decreased Ca absorption and a compensatory increase in PTH production." (PMID 25886405, 2015). "The cause of normal to low PTH levels in patients with VDD and liver disease is unclear." (PMID 26989059, 2016). "In this study, prebariatric surgery PTH levels did not correlate with improved liver disease status following surgery." (PMID 35265372, 2022). "In contrast to the change of vitamin D3, there was an upward trend of intact PTH along with the severity of liver disease, although no statistical difference was found." (PMID 27399065, 2016). "Finally, although we collected and adjusted for as many risk factors and laboratory findings as possible, we had no data on liver disease (gamma glutamyl transferase levels) and bone disease (parathyroid hormone levels) from our cohort." (PMID 26580067, 2015).
multiple myeloma (22 papers, 2010 to 2025). "Positive effects of PTH on preventing MM bone disease and promoting bone anabolism were associated with reduced growth of Hg myeloma cells, which was assessed by measuring hIg in mice sera, in SCID-rab mice and SCID-hu mice." (PMID 21188144, 2010). "Taken together, our data indicate that PTH pretreatment effectively increased bone mass, and this effect was associated with inhibition of myeloma cell engraftment and MM progression." (PMID 21188144, 2010). "We hypothesized that serum PTH might be associated with various clinicopathological parameters in multiple myeloma (MM)." (PMID 24967406, 2014). "In this study, we demonstrated that PTH is capable of increasing bone mass in myelomatous bones in vivo and that the increased bone formation is associated with a concomitant reduction in growth of the Hg myeloma cell line and primary myeloma cells from certain patients." (PMID 21188144, 2010). "Given that osteolytic lesions can occur in other hematological malignancies (i.e., multiple myeloma), ruling out concurrent disease is necessary (i.e., serum protein electrophoresis, parathyroid hormone)." (PMID 35846060, 2022). "Four mechanisms are implicated in this metabolic disorder, including excess parathyroid-related peptide secretion, focal osteolysis secondary to bone metastasis or multiple myeloma, excess calcitriol production, and ectopic parathyroid hormone production." (PMID 34401137, 2021). "The effects of PTH pretreatment on tumor growth were monitored for 8–12 weeks after inoculation with myeloma cells (see schema)." (PMID 21188144, 2010). "Total RNA was extracted from human bones of SCID-hu mice engrafted with Hg myeloma cells and treated with saline or PTH for 4 weeks." (PMID 21188144, 2010). "The significant downregulation of DKK1 that resulted from PTH treatment emphasizes the critical role of this factor in myeloma-induced suppression of osteoblastogenesis." (PMID 21188144, 2010). "Pretreatment with PTH before injecting myeloma cells increased bone mineral density of the implanted bone and delayed tumor progression." (PMID 21188144, 2010). "Treatment with PTH also downregulated markers typically expressed by osteoclasts and myeloma cells, and altered expression of genes that control oxidative stress and inflammation." (PMID 21188144, 2010). "Because PTH pretreatment resulted in increased bone mass, it is possible that myeloma cell injection into these bones was less efficient and resulted in fewer cells reaching the bones, which would contribute to the appearance of an antimyeloma effect." (PMID 21188144, 2010). "The GEP data provided important insights into molecular mechanisms that mediate reduced myeloma growth after PTH treatment." (PMID 21188144, 2010). "PTH resulted in increased bone mineral density of myelomatous bones and reduced tumor burden, which reflected the dependence of primary myeloma cells on the bone marrow microenvironment." (PMID 21188144, 2010). "The luciferase assay demonstrated that the numbers of myeloma cells injected into the implanted bones of PTH-pretreated hosts were similar to those injected into saline-pretreated hosts." (PMID 21188144, 2010). "At the end of the experiments, BMD of the implanted bone in PTH-treated hosts was slightly lower than before myeloma cells were injected, but it was significantly higher than in saline-treated hosts (p>0.004)." (PMID 21188144, 2010). "SCID-rab (10 mice/group) and SCID-hu (eight mice/group) mice engrafted with Hg myeloma cells were treated with saline (as a control) or PTH for 4 weeks." (PMID 21188144, 2010). "Many of the genes demonstrated by GEP to have significantly altered expression after PTH treatment are relevant to bone remodeling, PTH signaling, and myeloma pathogenesis." (PMID 21188144, 2010).
multiple myeloma (continued). "We used Hg cells, along with the SCID-rab and SCID-hu model systems for MM, to characterize the effects of PTH on bone metabolism and on myeloma growth in myelomatous bone and to shed light on the molecular mechanisms of PTH." (PMID 21188144, 2010). "We exploited the SCID-hu system to shed light on molecular mechanisms involved in the effects of PTH treatment on bone remodeling and myeloma growth." (PMID 21188144, 2010). "The consequences of PTH pretreatment on bone mass before and after myeloma cell inoculation were also visualized on X-ray radiographs." (PMID 21188144, 2010). "The dynamics of IL-6 in PTH treatment models are simplistic compared to multiple myeloma models." (PMID 40012834, 2024). "Kang and colleagues studied serum PTH in 115 patients with multiple myeloma (a malignancy arising in the bone marrow from abnormal plasma cells) and found inferior progression-free survival in the group with high PTH levels compared to the group with normal PTH levels." (PMID 39141058, 2024). "According to the previous study, it was hypothesized that elevated PTH may mediate the induction of multiple myeloma (MM) through the downstream biologic effects of interleukin 6 (IL-6)." (PMID 24967406, 2014). "Furthermore, pretreatment with PTH resulted in delayed growth of myeloma cells taken from three additional patients." (PMID 21188144, 2010). "Upon establishment of MM tumor growth (indicated by hIg level >10 μg/ml), 10 SCID-rab hosts engrafted with myeloma cells from 10 patients were treated with PTH for 4 weeks; an additional 10 matching SCID-rab hosts served as controls and were treated with saline for 4 weeks." (PMID 21188144, 2010). "Treatment with PTH markedly increased the number of differentiating osteoblasts, but the number of osteoclasts remained unchanged in bones engrafted with Hg myeloma cells and was moderately reduced in bones engrafted with primary myeloma cells." (PMID 21188144, 2010). "We tested the effects of daily administered parathyroid hormone (PTH) on bone disease and myeloma growth, and we investigated molecular mechanisms by analyzing gene expression profiles of unique myeloma cell lines and primary myeloma cells engrafted in SCID-rab and SCID-hu mouse models." (PMID 21188144, 2010). "Treatment with PTH did not stop after inoculation of the myeloma cells, in order to prevent a potential increase in osteoclast activity and bone resorption after PTH withdrawal." (PMID 21188144, 2010). "These GEP observations support the findings that PTH promotes bone anabolism, does not increase osteoclast activity, and attenuates growth of myeloma cells in bone." (PMID 21188144, 2010). "After myeloma cell engraftment, BMD of the bones implanted in saline-treated hosts, but not in PTH-treated hosts, was significantly lower than (29±8%) before myeloma cells were injected (p<0.002)." (PMID 21188144, 2010). "Pretreatment with PTH significantly inhibited the growth of luciferase-expressing BN myeloma cells in SCID-rab mice (six mice/group) 5 weeks (p<0.004), 7 weeks (p<0.004), and 9 weeks (p<0.03) after inoculation with myeloma cells." (PMID 21188144, 2010). "Our study demonstrated not only that PTH has no direct stimulatory effects on myeloma cells but also, intriguingly, that PTH has antitumor properties, presumably due to its ability to alter the bone marrow microenvironment." (PMID 21188144, 2010). "Because PTH had no direct effects on growth of myeloma cells, we conclude that shifting bone turnover to an anabolic state in myelomatous bone results in negative effects on MM progression." (PMID 21188144, 2010). "His parathyroid hormone level was suppressed, and a myeloma screen was negative." (PMID 41362524, 2025).